AQP4 (aquaporin 4)
Diseases named in the same sentence as AQP4 in open-access papers (continued):
Sharing a sentence is not in itself a finding about the gene and the disease.
myelitis (continued). "In one study in 27 NMOSD patients with a history of myelitis and six NMOSD without history of myelitis and without spinal cord lesions (all participants AQP4 ab positive), MUCCA was reduced in both groups vs. healthy controls and correlated with clinical disability." (PMID 32625158, 2020). "During the follow-up, none of the children with AQP-4 Ab seropositive underwent attack of myelitis." (PMID 27725883, 2016). "Similarly, disease starts with isolated ON or myelitis rather than simultaneous ON and myelitis in the vast majority of AQP4-IgG-positive patients." (PMID 27793206, 2016). "AQP4-IgG can also be detected in other autoimmune disorders related to NMO such as Asian optic-spinal MS, recurrent ON, recurrent myelitis with LETM, ON or myelitis associated with certain organ-specific and non-organ specific autoimmune disorders." (PMID 26950113, 2016). "Most studies have found MOG-IgG exclusively in patients with ON and/or myelitis who are negative for AQP4-IgG, suggesting that MOG-IgG may denote a disease entity in its own right." (PMID 27788675, 2016). "Additionally, serum Abs to full length AQP4 were also detected in the patient with isolated myelitis, but not in the patient with SLE-myelitis, who were both positive for M-23 AQP4-IgG." (PMID 20463974, 2010). "A study comparing GFAP-IgG and AQP4-IgG related myelitis found that 20% of AQP4-IgG related myelitis patients experienced INVH as prodromal symptoms, while GFAP-IgG related myelitis patients did not." (PMID 39949796, 2025). "Crucially, the absence of CSF pleocytosis, autoantibodies (AQP4/MOG/MBP), and demyelinating markers differentiated this case from myelitis, while DSA confirmed the vascular etiology." (PMID 41137336, 2025). "Key reasons for exclusion included inadequate history of ON or myelitis, unclear MRI images, absence of LETM evidence, and inaccuracies in AQP4-IgG tests." (PMID 39735550, 2024). "Generally, we observed that AQP4-IgG + NMOSD patients had lower cervical cord volumes than MOGAD, both without and with myelitis." (PMID 38343712, 2024). "Similarly, our study provides indications of generally lower cervical cord volumes in AQP4-IgG + NMOSD patients with and without myelitis compared with MOGAD." (PMID 38343712, 2024).
transverse myelitis (115 papers, 2008 to 2026). "What clinical and radiological outcomes are associated with transverse myelitis in patients with myelin oligodendrocyte glycoprotein (MOG) antibody (Ab) disease or aquaporin-4 (AQP4)-Ab disease?" (PMID 31596489, 2019). "Presented in 2015, aged 53y with longitudinally extensive transverse myelitis and was found to meet diagnostic criteria for AQP4 + NMO." (PMID 29511864, 2018). "In the CLUE cohort, we explored alterations in the brain’s pyramidal tracts subsequent to long-segmental transverse myelitis in AQP-4-positive NMOSD patients." (PMID 40799281, 2025). "NMOSD is an acute or subacute autoimmune disease featuring acute optic neuritis and transverse myelitis, resulting from pathogenetic IgG autoantibodies against aquaporin 4 (AQP-4) or myelin oligodendrocyte glycoprotein." (PMID 39960645, 2025). "The keywords gradually changed from “transverse myelitis”, “nmo-igg”, “astrocyte”, “demyelination”, and “aquaporin-4” to “relapse”, “treatment”, “rituximab”, “plasma exchange”, “diagnosis”, and “magnetic resonance imaging”." (PMID 37346048, 2023). "NMOSD is an autoimmune condition primarily targeting the AQP4 protein, resulting in recurrent ON and transverse myelitis." (PMID 38046734, 2023). "She had gadolinium enhancing longitudinally extensive transverse myelitis on MRI and was AQP4-IgG positive on serum studies." (PMID 37667215, 2023). "In fact, AQP4-IgGs are found in half of the patients with longitudinally extensive spinal cord lesions, and transverse myelitis occurs in 12–56% of patients with MOGAD, depending on age and disease duration." (PMID 36330423, 2022). "During more than 2 years of follow-up after delivery, six patients with AQP4-ON experienced transverse myelitis with a duration of 10–120 months." (PMID 36507533, 2022). "Autoantibodies targeting AQP4 and MOG are the most frequent causes of antibody-associated transverse myelitis." (PMID 36330423, 2022). "Conversely, patients with SLE and evidence of transverse myelitis should be screened for anti-AQP4 antibodies." (PMID 36514583, 2022). "Four patients (7%) had primary progressive MS, 3 (5%) had radiologically isolated syndrome, 3 (5%) had aquaporin-4-IgG–positive NMOSD, and 1 (2%) had myelin oligodendrocyte glycoprotein-IgG–associated transverse myelitis." (PMID 32421186, 2020). "This cross-sectional study examines clinical and radiological outcomes among patients with myelin oligodendrocyte glycoprotein (MOG) antibody (Ab) disease or aquaporin-4 (AQP4)-Ab disease after experiencing a first transverse myelitis episode." (PMID 31596489, 2019). "A 26-year-old, 17-week pregnant woman developed aquaporin-4-IgG-positive severe longitudinally extensive transverse myelitis during the course of disseminated herpes zoster and became quadriparetic." (PMID 29552355, 2018). "A quarter of the MOG-seropositive (1/4) and about a third of the AQP4-seropositive (10/31) and seronegative (4/13) patients had a disease manifestation with transverse myelitis (TM)." (PMID 25889963, 2015). "Recently, it was reported that vitamin D levels were lower in patients with recurrent transverse myelitis (TM) (n = 33; 61% AQP4-Ab positive) than in those with monophasic TM (n = 44; 0% AQP4-Ab positive)." (PMID 25211011, 2014). "In a review of literature by Jarius and Wildemann, the frequency of anti-AQP4 antibody in patients with longitudinally extensive transverse myelitis (LETM) ranged between 0% and 100% with a median of 53.3%." (PMID 25548676, 2014). "Affected individuals may present with hemiparesis, dysarthria, and elevated aquaporin-4 (AQP-4) antibodies, leading to extensive transverse myelitis in the cervical spinal cord." (PMID 41403967, 2026). "The diagnosis of seronegative NMOSD relies on the presence of at least two different clinical manifestations of NMOSD, one being ON, transverse myelitis or AP, with evidence of consistent demyelinating lesions on MRI and negativity of AQP4-IgG tested with the best available assay." (PMID 35401423, 2022).
transverse myelitis (continued). "Systemic Lupus Erythematosus (SLE) may present with longitudinally extensive transverse myelitis which may co-occur with MS and with AQP4-IgG positive NMOSD or be a sign of lupus myelitis." (PMID 32671002, 2020). "Although fatigue was worse in AQP4‐Ab patients compared to MOG‐Ab patients (P = 0.008) in all patients as well as in those who ever had transverse myelitis (P = 0.023), this was driven by the differences in age, disability and pain interference rather than antibody subtype itself." (PMID 32187851, 2020). "A 59-year-old patient was diagnosed with AQP4-IgG seropositive NMOSD upon presentation with paraplegia, and MRI-confirmed longitudinally extensive transverse myelitis from C2 to T5 in November 2023." (PMID 41562061, 2025). "It is characterised by the presence of longitudinally extensive transverse myelitis (LETM) and antibodies against water channel aquaporin-4 (AQP4-immunoglobulin G [IgG])." (PMID 37941871, 2023). "Another case of a young patient presenting longitudinally extensive transverse myelitis with medulla oblongata involvement in the presence of both GFAP-IgG and AQP4 antibodies has also been described." (PMID 34279454, 2021). "In 2006, Wingerchuk and colleagues proposed the diagnostic criteria for NMO that require ON, transverse myelitis (TM), and at least two of three supportive criteria: contiguous spinal cord MRI lesion extending over three or more segments, brain MRI non-diagnostic for MS, or AQP4-IgG seropositivity." (PMID 35054412, 2021). "Transverse myelitis occurred at onset of disease for 32 patients (70%) with MOG-Ab disease and 57 patients (78%) with AQP4-Ab disease." (PMID 31596489, 2019). "Antibodies to AQP4 were also present in the serum of longitudinally extensive transverse myelitis (LETM) patient and plasma exchange was paralleled by disappearance of AQP4-Ab and sustained clinical improvement." (PMID 30555637, 2018). "In up to 40% of cases, transverse myelitis can be the presenting manifestation of NMOSD The presence of a LETM almost always evokes the diagnosis of AQP4-NMOSD." (PMID 29064441, 2017). "The presence of a short segment (<3 vertebral segments) transverse myelitis (i.e., SSTM) was reported in 14% of patients with AQP4-NMOSD and most recently in patients with MOG-NMOSD." (PMID 29064441, 2017). "Furthermore, all patients with overlapping AQP4 antibodies responded poorly to first-line immunotherapy (IVMP, IVIG) in the acute phase, and two of them presented with longitudinally extensive transverse myelitis." (PMID 37350972, 2023). "Anti-AQP4 Ab also proved to be helpful in predicting a more severe course and a probable conversion to NMO after a first episode of isolated optic neuritis or longitudinally extensive transverse myelitis." (PMID 23710199, 2013). "These disorders include neuromyelitis optica (NMO, also known as unilateral optic neuritis), isolated or recurrent transverse myelitis, longitudinally extensive transverse myelitis or isolated brain lesions with or without detectable anti AQP4-IgG autoantibody." (PMID 37828019, 2023). "Differential diagnoses included NMOSD and MOGAD, which were excluded based on characteristic radiologic patterns, negative aquaporin-4 and MOG antibodies, and the absence of longitudinally extensive transverse myelitis." (PMID 41503332, 2025). "In this study, 62.2% of the studied patients were positive for AQP4-IgG Abs, and none of them had been diagnosed with NMODS features or transverse myelitis at the time of recruitment to the study." (PMID 37208665, 2023). "Although the patient tested negative for antibodies to AQP-4 and myelin oligodendrocyte glycoprotein, she was diagnosed with NMOSD in February 2017, based on recurrent episodes of longitudinal extensive transverse myelitis, MRI changes, and area postrema syndrome." (PMID 34025563, 2021).
transverse myelitis (continued). "Examples include isolated unilateral or simultaneous bilateral or recurrent optic neuritis (ON); isolated or recurrent transverse myelitis (TM); typical NMO brain lesions (hypothalamus, corpus callosum, brainstem, periventricular) with or without detectable anti AQP4-IgG autoantibody." (PMID 25921037, 2015).
autoimmune disease (111 papers, 2008 to 2026). A disorder resulting from loss of function or tissue destruction of an organ or multiple organs, arising from humoral or cellular immune responses of the individual to their own tissue constituents. "One proposed mechanism for this association suggests that these autoimmune diseases induce the production of inflammatory cytokines, which in turn activate AQP4-specific T cells, leading to the onset of NMOSD." (PMID 40018473, 2025). "SLE and Sjögren syndrome are the most prevalent associated autoimmune diseases in AQP4-NMOSD, followed by myasthenia gravis and thyroiditis." (PMID 34097296, 2022). "In conclusion, the findings in this study indicated the pathogenic roles of disease-susceptible HLA alleles in the development of NMOSD, an autoimmune disease characterized by the production of anti-AQP4 autoantibodies." (PMID 34997058, 2022). "In previous studies, NMOSD with AQP4-IgG+ has been shown to be associated with a high frequency of autoantibodies and autoimmune diseases including SLE, RA, Sjogren’s syndrome (SS), myasthenia gravis (MG), and antiphospholipid syndrome (APS)." (PMID 34367251, 2021). "As an autoantibody-mediated autoimmune disease, the exact immune checkpoints where loss of immune tolerance to AQP4 in AQP4-IgG positive NMOSD occur are uncertain." (PMID 34445343, 2021). "Compared with MS, AQP4-Ab-positive NMO is more frequently associated with other autoimmune diseases such as myasthenia gravis, systemic lupus erythematosus, Sjögren’s syndrome, celiac disease, and sarcoidosis." (PMID 24272588, 2014). "Neuromyelitis optica/Devic’s disease is an autoimmune disease involving the spinal cord and optic nerve that is associated with autoantibodies against aquaporin-4 and interestingly antibodies against MOG." (PMID 24223903, 2013). "Importantly, AQP4-IgG testing should be performed in patients with underlying autoimmune diseases who develop neurological symptoms suggestive of NMOSD." (PMID 40698091, 2025). "NMOSD is an autoimmune disease of the central nervous system with a predominantly humoral immune profile, a spectrum of autoimmune CNS inflammatory demyelinating disorders closely associated with antibodies to aquaporin-4 (AQP4)." (PMID 39029081, 2024). "The finding that a positive anti-AQP4-IgG status is significantly associated with the presence of other autoimmune diseases in addition to NMOSD might indicate that anti-AQP4 is indeed a “bystander” B cell response." (PMID 33776892, 2021). "The primary pathology of NMOSD involves astrocyte damage caused by anti-AQP4 antibody, and an association between NMOSD and other autoimmune diseases has been recognized." (PMID 40018473, 2025). "Instead, a multidisciplinary approach, incorporating neuroimaging, serological markers such as AQP4-IgG, and patient demographics, provides the most robust framework for distinguishing among these autoimmune diseases." (PMID 40486405, 2025). "The CROCTINO dataset revealed a higher prevalence of multiple comorbidities and autoimmune disorders in AQP4‐NMOSD than in MOGAD and DN‐NMOSD." (PMID 40485599, 2025). "This autoimmune disease is characterized by the presence of aquaporin-4 immunoglobulin G antibodies (AQP4-IgG) in the patient’s serum." (PMID 39941228, 2025). "Neuromyelitis optica spectrum disorder (NMOSD), characterized by aquaporin-4 immunoglobulin G (AQP4-IgG), is a rare autoimmune disorder with an incidence rate of 0.039–0.73 per 100,000 person-years and a striking female predominance (9:1 ratio)." (PMID 40568579, 2025). "Anti-neural antibodies have been identified as key diagnostic biomarkers for autoimmune diseases of the central nervous system, such as the pathogenic roles of anti-NMDAR and anti-LGI1 antibodies in autoimmune encephalitis, and anti-AQP4 antibodies in NMOSD." (PMID 39965877, 2025).
autoimmune disease (continued). "Autoimmune diseases were also frequent in AQP4‐NMOSD, including systemic lupus erythematosus (SLE) (n = 17), Sjögren's syndrome (n = 11), myasthenia gravis (n = 9), and autoimmune thyroiditis (Hashimoto's disease) (n = 5)." (PMID 40485599, 2025). "Preoperative multidisciplinary consensus deemed the spinal cord lesions diagnostically equivocal, given the concurrent GFAP-IgG and AQP4-IgG positivity raising suspicion of autoimmune disease." (PMID 40688088, 2025). "Previous studies have shown that coexisting autoimmune disorders are present in more than one third of AQP4-IgG patients (e.g., systemic lupus erythematosus or Sjögren syndrome)." (PMID 38342798, 2024). "Approximately one in four patients with AQP4-IgG positive NMOSD have another coexisting autoimmune diseases, with systemic lupus erythematosus (SLE), rheumatoid arthritis (RA), and Sjögren’s syndrome (SS) being the most common complications." (PMID 38899058, 2024). "The safety profile of CAR T-cell treatment for highly inflammatory, CNS-targeted autoimmune disorders like relapsing MS is still unclear while it is well established for several effective mAbs approved for MS or AQP4-positive NMOSD." (PMID 39276207, 2024). "NMOSD is an autoimmune disease in which anti-AQP4 antibodies activate both the complement cascade and DNA damage pathways, promoting inflammatory cell infiltration and resulting in AQP4 depletion, astrocyte death, demyelination, and neuronal loss." (PMID 39543281, 2024). "Recent studies found that AQP4-IgG can present alone or in conjunction with other autoimmune disease antibodies in the patient’s body, indicating the coexistence relationship between NMSOD and autoimmune diseases." (PMID 37173637, 2023). "Seventy-one (11%) patients had concomitant autoimmune diseases, and 572 (89%) patients were AQP4-IgG seropositive." (PMID 37350969, 2023). "Together, these findings further underline the more pronounced role of complement activation in autoimmune diseases directed against AQP4 compared with MOG." (PMID 36414427, 2023). "Our results suggest that the pathomechanisms of MOG-Ab production are different from those of AQP4-Ab positive NMOSD, in which the pathogenic autoantibody is continuously produced and other coexisting autoimmune diseases occur more frequently than MOG-AD." (PMID 34991631, 2022). "It has recently been shown that the lack of AQP4 in the retina during inflammation resulted in impaired clearing of retinal swellings and provoked astrogliosis and loss of ganglion cells, indicating a protective role of AQP4 in autoimmune diseases in the CNS." (PMID 36241864, 2022). "At present, the treatment protocols for patients with MOG-abs are mostly based on limited retrospective research and treatment experience from other autoimmune diseases, such as AQP4-ab-positive NMOSD." (PMID 33841310, 2021). "Although the frequency of coexistent autoimmune diseases seems to be lower than AQP4‐Ab‐positive patients, comorbidity with other autoimmune disorders has been reported in MOG‐EM patients." (PMID 33319460, 2021). "Neuromyelitis optica (NMO) is a rare autoimmune disorder mediated by self-reactive T and B cells, and an antibody against the aquaporin 4 (AQP4) channel protein of astrocytes." (PMID 34987468, 2021). "Autoimmune diseases with well-known target antigens, such as AQP4+ NMOSD and MOGAD, are good candidate diseases to investigate tolerance-inducing cell-based therapies, especially in an antigen-specific way." (PMID 34360690, 2021). "ANAs were reported to be more frequently exist in NMO‐IgG‐seropositive patients, while another report also showed that patients with AQP4(+) were more likely to have coexisting autoantibodies (45/97, 46,4%) and autoimmune disorders (31/130, 23.8%)." (PMID 33319460, 2021). "Similar as what has been described in other autoimmune diseases, a reduction in anti-AQP4 status would have been conceivable." (PMID 33776892, 2021).